EGFR (epidermal growth factor receptor)
Diseases named in the same sentence as EGFR in open-access papers (continued):
Sharing a sentence is not in itself a finding about the gene and the disease.
breast carcinoma (continued). "Synergistic interaction of GPR30 and the EGFR signaling pathway enhances breast cancer proliferation, which allows tumor progression in the presence of tamoxifen." (PMID 24289103, 2013). "Given the receptor dependent role, SSTR2 and ORs regulating the MAPK and PI3K/AKT pathways in breast cancer cells is an indication of inhibition of EGFR functions." (PMID 24059654, 2013). "Epidermal growth factor receptor (EGFR) targeting agents are successfully used in different cancer entities like lung or breast cancer." (PMID 23792785, 2013). "In breast cancers, the EGFR protein is overexpressed and is considered a potential therapeutic target." (PMID 23844004, 2013). "EGFR and IGF-1R are commonly overexpressed in a significant number of cancers, included breast cancer, and its overexpression have been implicated to influence the response to irradiation in breast cancer cells." (PMID 23777562, 2013). "Cetuximab a chimeric monoclonal antibody was employed to target EGFR and showed a lower response in an advanced stage Triple negative breast cancer." (PMID 29147345, 2013). "Other mechanisms also reported the antimetastatic potential of CTXIII in breast cancer, such as EGFR signaling and PI3K/Akt and p38 MAPK signaling." (PMID 23710144, 2013). "Anti-EGFR antibody conjugated fluorescent nanoparticles (FNs probe) showed good sensitivity and exceptional photostability for breast cancer cell imaging." (PMID 23533377, 2013). "Simultaneously, constitutively activated EGFR (EGFRvIII) expressing breast cancer cells exhibited the inhibition of EGFRvIII phosphorylation due to DPDIM treatment." (PMID 23555785, 2013). "In aggregate, these data demonstrate that elevated autophagic flux is an early response to gefitinib and that targeting EGFR and autophagy should be considered when developing new therapeutic strategies for EGFR expressing breast cancers." (PMID 24146879, 2013). "KIT is co-expressed with EGFR and is associated with BRCA1-mutation carriers and in sporadic basal-like breast cancer." (PMID 23593654, 2013). "The STAT5 pathway has been shown to mediate PRLR activity and regulate mammary gland development, differentiation, and proliferation, whereas EGFR is a central growth factor pathway in mammary gland development and a subset of breast cancers." (PMID 23938070, 2013). "A subpopulation of TNBCs exhibit a basal-like morphology with immunohistochemical positivity for cytokeratins 5/6 (CK5/6) and/or epidermal growth factor receptor (EGFR), and have a high incidence of BRCA (breast cancer susceptibility) mutations." (PMID 24004841, 2013). "Erlotinib was shown to be more sensitive in the doxorubicin-resistant human breast cancer cell lines and paclitaxel-resistant human ovarian cancer cell lines and the sensitivity was positively correlated with EGFR expression." (PMID 23590835, 2013). "In this study, we synthesized a TAT-based Y211F cell-penetrating PCNA peptide (CPPP) that blocks Y211 phosphorylation and inhibits growth of triple-negative and EGFR TKI-resistant breast cancer cells." (PMID 23593472, 2013). "In breast cancer, ROS mediate EGFR-tyrosine kinase inhibitor gefitinib resistance, and the hydrogen peroxide scavenger catalase was able to sensitize those cells to gefitinib treatment." (PMID 23434665, 2013). "We noted that GPR30 activation increased ligand-dependent EGFR activity, leading to an Erk1/2-mediated transcriptional response, thus contributing to the development of tamoxifen resistance in breast cancer cells." (PMID 24289103, 2013). "Triple-negative breast cancer cell lines were treated with proteasome inhibitors in combination with lapatinib (a dual epidermal growth factor receptor (EGFR)/HER2 tyrosine kinase inhibitor)." (PMID 24216290, 2013). "In breast cancer patients, EGFR-targeted therapy suppresses tamoxifen-resistant tumor progression; however, the initial activator of the EGFR signaling pathway is disputed." (PMID 24289103, 2013).
breast carcinoma (continued). "Recently, PTPN12 was found to interact with and dephosphorylate the RTKs EGFR and ErbB-2, thereby acting as a tumor suppressor in breast cancer by suppressing MAPK signaling." (PMID 23785422, 2013). "To date, the results from the preclinical and early clinical cancer prevention trials studying the effectiveness of EGFR inhibitors as viable preventive strategies for women with HER2-positive breast cancer are very promising." (PMID 24069582, 2013). "Several randomized clinical studies of anti-EGFR therapy reported that fewer than 20% of metastatic TNBCs showed response to anti-EGFR therapy and the use of these therapies for targeted breast cancer treatment has been controversial." (PMID 24205362, 2013). "We found no change in HER2 and HER3 expression and phosphorylation, whereas phospho-EGFR level of the ZR-75-1 cell line decreased like the other mentioned breast cancer cell lines." (PMID 23555785, 2013). "It has been suggested, for example, that reporter labeled EGF can activate the EGFr signaling pathway in breast cancer xenografts." (PMID 23331017, 2013). "The electrotaxis of A549 lung adenocarcinoma cells and MDA-MB-231 breast cancer cells are shown to involve the epidermal growth factor receptor (EGFR) pathway." (PMID 23951353, 2013). "Breast cancer cells that express ER can be directly stimulated via estrogen, or indirectly stimulated via epidermal growth factor receptor (EGFR) or insulin growth factor receptor (IGFR)." (PMID 23984412, 2013). "SFK have been demonstrated in lung tumor tissues and Src phosphorylates EGFR Y-845 in breast cancer cells." (PMID 23866081, 2013). "Our data support the therapeutic utility of combination treatment strategies based on targeting EGFR and autophagy in breast cancer." (PMID 24146879, 2013). "STAT3 is also a downstream target of receptors in the epidermal growth factor receptor (EGFR) family, and several of these have been implicated in the stimulatory effect of wound healing on HNSCC cells and breast carcinoma." (PMID 23351302, 2013). "One of the defining features of basal-like breast cancer is epidermal growth factor receptor (EGFR) overexpression." (PMID 24499560, 2013). "Our earlier report has shown that hypoxia leads to the abnormal accumulation of EGFR and subsequent alteration of cell signaling in breast cancer." (PMID 23431444, 2013). "For example, in SUM229 breast cancer cells, Src activation and Y845 phosphorylation of EGFR depend upon the activity of Met, as judged by the effects of the Met-specific activator (HGF) and inhibitors (SU11274)." (PMID 23702846, 2013). "It is interesting to note that many selective signaling pathways (ERK, p-AKT) are highly activated due to specific gene overexpression such as EGFR in highly aggressive breast cancers." (PMID 23762292, 2013). "EGFR signaling has been extensively studied in breast cancer, showing both EGFR gene amplification and protein overexpression (14–91% cases), thus leading to poor prognosis and relapse." (PMID 23555785, 2013). "Recent studies demonstrated that C/EBP-β is a negative regulator of miR-145 via activation of the Akt pathway in breast cancer cells, and that EGFR downregulates miR-145 in colon cancer cells." (PMID 23390502, 2013). "Clinical testing of EGFR tyrosine kinase inhibitors (TKIs) in advanced breast cancer patients demonstrated that EGFR TKIs are ineffective in treating this disease even though EGFR is overexpressed." (PMID 23593472, 2013). "Preclinical and clinical studies have shown that patients with ER+ breast cancer that over-expresses EGFR and HER-2 have a lower sensitivity or shorter duration of response to hormone therapy." (PMID 24289103, 2013). "In breast cancer, the expression of epidermal growth factor receptor (EGFR) is also closely related to the maintenance of CSCs." (PMID 23527117, 2013).
breast carcinoma (continued). "Seven of these mutations were activating mutations and all of these mutations were sensitive to the irreversible HER2/EGFR tyrosine kinase inhibitor neratinib, thus validating HER2 somatic mutations as drug targets for breast cancer treatment." (PMID 23734345, 2013). "These live areas within mammary tumors display some intrinsic mechanisms that can partially explain their growth in spite of ER signaling, such as increased expression of EGFR and/or HER2." (PMID 23634930, 2013). "Our group has shown that HER2-transgenic mice treated with the HER2/EGFR dual kinase inhibitor lapatinib or the EGFR inhibitor gefitinib have delayed development of HER2-positive mammary tumors." (PMID 24069582, 2013). "Specific pharmacological inhibitors and gene-silencing procedures were used to show that BPA induces the expression of the GPER target genes c-FOS, EGR-1, and CTGF through the GPER/EGFR/ERK transduction pathway in SKBR3 breast cancer cells and CAFs." (PMID 22552965, 2012). "Anti-EGFR therapy has been increasingly recognized as an important treatment for breast cancer patients." (PMID 22355336, 2012). "Breast cancers also overexpress the epidermal growth factor receptor (erbB1), and the presence of this growth factor receptor has been linked to a higher proliferative potential and a worsened prognosis and resistance to hormonal therapy." (PMID 22666610, 2012). "The roles that EGFR and its ligands play in breast carcinoma are a subject of intensive study and controversy." (PMID 23046633, 2012). "Intravenously injected exosomes delivered let-7a to xenografted EGFR-expressing breast cancer tissue in Rag2-/- mice." (PMID 26082068, 2012). "The EGFR signalling network plays a central role in breast cancer biology and the cell lines used have previously been shown to retain much of the biological heterogeneity of primary tumours." (PMID 22578440, 2012). "In vitro, afatinib has demonstrated anti-proliferative activity in HER2-positive and in “triple negative” breast cancer cell lines, including the EGFR-expressing SUM 190 and SUM-149 cell lines." (PMID 22763464, 2012). "A new nanobioconjugate was designed and synthesized, which specifically delivered anti-EGFR Morpholino antisense oligonucleotides (AON) into breast cancer cells and efficiently inhibited tumor growth in vivo." (PMID 22355336, 2012). "Several anti-EGFR agents are currently undergoing clinical testing in breast cancer patients clinically." (PMID 22905152, 2012). "In the context of a detailed analysis of breast cancer, the quantification of active epithelial growth factor receptor (EGFR) in clinical specimen is a prominent example for the application of a radio-ligand binding assay." (PMID 22577549, 2012). "The expression rates for EGFR ranged from 5% to 65% in breast carcinomas and from 45% to 72% in BLBCs, depending on the methodology used in different studies." (PMID 23082819, 2012). "Versican G3 enhanced breast cancer cell invasion to bone stromal cells or osteoblast cells appears to occur through enhancing EGFR/ERK or AKT signaling." (PMID 22862967, 2012). "Taken together, these results reveal that EBP50 can block EGF-induced EGFR phosphorylation in breast cancer cells." (PMID 22476347, 2012). "The dual EGFR/ERBB2 tyrosine kinase inhibitor lapatinib is currently used as an adjuvant therapy in breast cancer." (PMID 23028451, 2012). "Here we demonstrate that treatment of breast cancer cells sensitive to EGFR TKIs with recombinant HGF confers a resistance to EGFR TKIs." (PMID 22788954, 2012). "EGFR that is overexpressed in MDA-MB-231 and Hs578T cells has been associated with poor survival in basal-like breast cancers." (PMID 23158001, 2012). "Taken together, these in vitro assays confirm that inhibition of EGFR by PAR34 or shRNA decreases breast cancer cell motility." (PMID 22276166, 2012).
breast carcinoma (continued). "Our unexpected findings with AREG antibody treatments of cancer cells in the bone marrow encourage a more careful analysis of the impact of various inhibitors on EGFR signaling on all cell types in the breast cancer bone metastasis microenvironment." (PMID 22276166, 2012). "Breast cancer images were analyzed using an algorithm that quantitates the extent of staining in Ki-67 immunostained images, and EGFR immunostained colorectal cancer images were analyzed with an automated tumor segmentation algorithm." (PMID 22436596, 2012). "To inhibit breast cancer cell autocrine and paracrine signaling, we used shRNA to the EGFR as well as a monoclonal antibody (PAR34)." (PMID 22276166, 2012). "Because we have previously shown that hyperactivation of the EGFR pathway mimics oncogenic PIK3CA mutations, our results would suggest that breast cancers with mutant PIK3CA and AR expression would have a favorable therapeutic response to AR ligand binding." (PMID 22321971, 2012). "Many studies have proved that expression of EGFR in breast carcinoma is significantly higher than in normal epithelial tissue." (PMID 23046633, 2012). "A combination clinical trial (NCT01245205) with the Akt inhibitor MK-2206 and the dual EGFR/HER2 inhibitor lapatinib is in progress with patients having advanced or metastatic solid tumors or breast cancer patients." (PMID 23085539, 2012). "A recent study investigated the antitumor effects of trastuzumab (a monoclonal antibody against EGFR-2) in combination with glycolysis inhibitor 2-DG in ErbB2-positive breast cancer." (PMID 22844340, 2012). "In summary our intriguing and novel results point to the potential broader utility of PARP inhibitors in breast cancer beyond hereditary BRCA1-and BRCA2-deficient tumors by combining it with EGFR inhibitors such as lapatinib." (PMID 23071597, 2012). "In breast cancer, EGFR and HER3 expression are substantially increased after long-term trastuzumab exposure." (PMID 23198146, 2012). "For example, TG2 has been identified as a downstream target of EGFR, and EGFR expression level is known to significantly vary in various breast cancer cell lines including MCF-7 and T-47D cells." (PMID 22759359, 2012). "The most well documented example involves the frequency of activating mutations in the EGFR oncogene and copy number differences of the EGFR locus for certain types of lung and breast carcinomas." (PMID 23029043, 2012). "High expression of EGFR induces erroneous development and unrestricted proliferation in a number of human malignancies, including breast cancer." (PMID 22355336, 2012). "Metastatic breast cancers that overexpress Her2 (epidermal growth factor receptor (EGFR) related tyrosine kinase) are treated with Herceptin, a monoclonal antibody." (PMID 22564335, 2012). "Anti-EGFR therapy has been increasingly recognized as a potential treatment for breast cancer patients, and recently, advances in this direction have been made." (PMID 22355336, 2012). "As far as HER2/neu and EGFR expression in feline primary cultures, both proteins were expressed in all mammary carcinoma cultures." (PMID 22417013, 2012). "EGFR signaling regulates biological processes important for the pathogenesis of human cancers, including lung cancer, breast cancer, and prostate cancer." (PMID 22991510, 2012). "EGFR overexpression is also important in the survival of breast cancer cells under low-glucose culture conditions, this effect being independent of its protein kinase activity." (PMID 22570721, 2012). "A luciferase-transfected breast cancer cell (epidermal growth factor receptor+, MDA-MB-468luc cells) was produced and used for both in vitro and in vivo experiments for monitoring the cell killing effect of PIT." (PMID 22873679, 2012).
breast carcinoma (continued). "It has been proposed that KAI1 attenuates EGFR signaling and inhibits cell motility in breast cancer." (PMID 22390300, 2012). "For example, EGFR/HER2-MAPK axis is important in human breast cancer while the kinase activity of the HER2/ErbB3 axis plays a major role in the DNA binding and androgen receptor stability in prostate cancer." (PMID 22991510, 2012). "HER2, one of members in the epidermal growth factor receptor (EGFR) family, is a key player in breast cancer." (PMID 23130020, 2012). "Using different methods to knock down HER3 expression, inhibition of breast cancer cell growth was more potent than knocking down EGFR." (PMID 23198146, 2012). "The ERBB2 receptor tyrosine kinase, a member of the epidermal growth factor receptor (EGFR) family, is overexpressed in 20-30% of primary human breast cancers, and expression correlates with poor patient outcome." (PMID 22621282, 2012). "The present nanobioconjugates were designed to target breast cancer with 2C5 anti-tumor mAb and to inhibit the protein synthesis of EGFR by specific AON." (PMID 22355336, 2012). "The EGFR is frequently expressed in the basal subtype of breast cancer, which typically lack the expression of estrogen receptor α (ERα), progesterone receptor (PR) and Her2 receptor, accounting for only ∼15–20% of the total disease." (PMID 22276166, 2012). "Consistent with a central role for the breast cancer cell EGFR in the stimulation of osteoclastogenesis, the addition of exogenous AREG to co-cultures containing shEGFR-MDA-231cell failed to induce increased numbers of the bone resorbing cells." (PMID 22276166, 2012). "The second study utilized DHA alone, and similarly reported an alteration in EGFR localization in lung and breast cancer cell lines." (PMID 22761867, 2012). "Clinical testing of EGFR tyrosine kinase inhibitors (TKIs) in breast cancer patients led to the conclusion that EGFR TKIs are ineffective in treating this disease." (PMID 22788954, 2012). "Consistent with its suspected role as an endocrine disruptor, the estrogen-dependent breast cancer signaling pathway was marginally enriched (p-value = 0.043) because three genes (EGFR, ESR1 and CCND1) were used to make the inference." (PMID 23144783, 2012). "In recent studies, GPR30 was reported to regulate the GPR30-dependent activation of MAPK-ERK1/2 via EGFR transactivation in breast cancer and endometrial cancer." (PMID 23163984, 2012). "Combined treatment of general breast cancer cells with drugs that target EGFR and HER2 results in a synergistic antitumor effect." (PMID 22905152, 2012). "We also evaluated the correlation between miR-7 and EGFR expression in breast carcinoma cells derived from 21 patients using laser capture microdissection combined with quantitative reverse transcriptase-PCR." (PMID 23227519, 2012). "We have previously shown that inhibiting Met kinase activity in breast cancer cell lines with constitutive Met activation sensitizes these cells to EGFR TKIs." (PMID 22788954, 2012). "Many basal breast cancers express high levels of EGFR which results in activation of the Ras/Raf/MEK/ERK cascade." (PMID 23085539, 2012). "Targeted therapy for breast cancer has focused on receptor tyrosine kinases of the epidermal growth factor receptor (EGFR and ErbB) family, which provide critical checkpoints of cell fate decisions." (PMID 22397502, 2012). "Previous reports have shown that n-3 PUFA can alter the localization of EGFR within the plasma membrane of lung and breast cancer cells." (PMID 22761867, 2012). "Initially, a combination of EPA and DHA was shown to alter the localization of EGFR within the plasma membrane of a breast cancer cell line." (PMID 22761867, 2012). "Here, we show that exosomes can be used to deliver microRNA efficiently to epidermal growth factor receptor (EGFR)-expressing breast cancer cells." (PMID 26082068, 2012).